PSAT1 (phosphoserine aminotransferase 1)
Diseases named in the same sentence as PSAT1 in open-access papers (continued):
Sharing a sentence is not in itself a finding about the gene and the disease.
Pan (1 paper, 2022). "We analyzed the expression of PSAT1 and three kinds of RNA modified (10 m1A types, 13 m5C types, and 21 m6A types) marker genes in Pan cancer." (PMID 36105075, 2022). "Therefore, we analyzed in detail the role and possible mechanism of PSAT1 in Pan cancers." (PMID 36105075, 2022).
phyllodes tumor (1 paper, 2018). A benign, borderline, or malignant fibroepithelial neoplasm arising from the breast and rarely the prostate gland. "The expression of serine–glycine biosynthetic genes including PHGDH, PSAT1 and GLDC is correlated to tumor grade and shorter disease-free survival in patients with phyllodes tumor." (PMID 29911072, 2018).
rectum cancer (1 paper, 2022). "Additionally, overall survival (OS) was plotted using patient-derived data from rectum cancer patients and made the distinction between low and high expression of PHGDH, PSAT1 and PSPH." (PMID 36291844, 2022).
rhabdomyosarcoma (1 paper, 2024). A rare aggressive malignant mesenchymal neoplasm arising from skeletal muscle. "Phgdh and Psat1 were 5.3-fold and 14.3-fold more expressed in YAP-driven rhabdomyosarcomas than in skeletal muscle, to which expression was compared." (PMID 38183459, 2024).
schizotypal personality disorder (1 paper, 2018). A disorder characterized by an enduring pattern of inability to establish close relationships coupled with cognitive or perceptual distortions, odd beliefs and speech, and eccentric behavior and appearance. "There is also evidence that the gene is implicated in SCZ based on a study of gene expression in a family with a chromosomal translocation near PSAT1 associated with SCZ and schizotypal personality disorder." (PMID 29942251, 2018).
skin cutaneous melanoma (1 paper, 2022). "PSAT1 alterations are more frequently found in UCEC patients with a mutation than in skin cutaneous melanoma patients." (PMID 36105075, 2022).
squamous cell carcinoma (1 paper, 2024). A carcinoma arising from squamous epithelial cells. "In the TCGA datasets of the two main subtypes of NSCLC, adenocarcinoma (LUAD) and squamous cell carcinoma (LUSC), PSAT1, SHMT1, SHMT2, MTHFD1 and MTHFD2 were significantly overexpressed compared to normal lung tissue." (PMID 38515202, 2024).
uveal melanoma (1 paper, 2022). A melanoma derived from melanocytes of the uveal tract. "Many cancer species, such as uveal melanoma (UVM), OC, UCEC, GBM, LUSC, etc., showed positive correlations between PSAT1 expression and RNA modification." (PMID 36105075, 2022).
cancer (106 papers, 2008 to 2025). A tumor composed of atypical neoplastic, often pleomorphic cells that invade other tissues. "Overexpression of PSAT1–the second key enzyme in the SSP–is implicated in the progression of various malignant tumors." (PMID 41415540, 2025). "A pan-cancer analysis of PSAT1 suggested associations between PSAT1 levels and immune infiltration, specifically, of CD8+ T cells, CD4+ T cells, macrophages, neutrophils, and dendritic cells." (PMID 40612679, 2025). "In recent years, an increasing number of investigations have shown that PSAT1 is highly associated with the occurrence, development, treatment, and prognosis of various cancers." (PMID 38614981, 2024). "PSAT1, an enzyme involved in serine biosynthesis, has been associated with promoting cell proliferation and survival in cancer cells." (PMID 39628390, 2024). "Although there are many experimental data which show an association of PSAT1 and biological behavior of malignant tumors, there are sparse data on its involvement in chemoresistance." (PMID 37376060, 2023). "Among the main findings of our study is the association between PSAT1 expression and immune infiltration in a variety of cancers, especially BRCA, Luminal, and LGG." (PMID 36105075, 2022). "The results of immunoassay showed that PSAT1 was associated with immune cell infiltration in multiple cancer species." (PMID 36105075, 2022). "Our results also suggested that PSAT1 is highly expressed in many malignant tumors and is associated with advanced stage of tumors." (PMID 36105075, 2022). "As the top gene of such risk assessment model, PSAT1 is deemed as a favorable prognostic marker in cancer." (PMID 33291071, 2020). "Next, GSEA was performed to examine biological pathways associated with PSAT1 in pan-cancer." (PMID 40612679, 2025). "Furthermore, miR-891b, which targets the phosphoserine aminotransferase 1 (PSAT1) gene, has been implicated in several cancers by regulating PSAT1 expression, potentially contributing to metastasis through EV-mediated signaling." (PMID 40867639, 2025). "Furthermore, we used multiple cancer cell lines containing p5372P or p5372R variants to further validate the endogenous interaction of PSAT1 and the p5372P variant." (PMID 36788227, 2023). "Consistently, PSAT1 knockout could change the morphology of cancer cell lines (PLC/PRF/5) containing p5372P variants and increase the mRNA level of CDH1." (PMID 36788227, 2023). "Furthermore, it was found that high PSAT1 expression was closely associated with bone metastasis in malignant tumors." (PMID 36061202, 2022). "PSAT1 may influence pan-cancer prognosis and is associated with immune infiltration, particularly for BRCA and LUSC." (PMID 36105075, 2022). "However, both PHGDH and PSAT1 are regulators and associated with an increased risk for multiple cancer progression and metastasis, indicating a possible link between dieting and cancers." (PMID 33921318, 2021). "The glutamate dependence of LUAD tumors harboring mutations to Nf1 and their susceptibility to PSAT1 inhibition may potentially be extended to additional cancers with alterations in the NF1–FAK1 pathway." (PMID 31036704, 2019). "The addiction of LUAD tumors harboring Nf1 mutations to glutamine made them susceptible to glutaminase and Psat1 inhibitors, a strategy that could potentially apply to additional cancers with alterations in the NF1–FAK1 pathway." (PMID 31036704, 2019). "Previous studies have shown that PSAT1 influences cancer cell behavior by modulating cell cycle progression and apoptotic pathways, as well as contributing to metabolic reprogramming." (PMID 40234836, 2025). "Elevated PSAT1 expression markedly enhances cancer cell proliferation, migration, and invasion, and is strongly correlated with poor patient prognosis in non-small cell lung cancer (NSCLC)." (PMID 41415540, 2025). "Second, these results further credential the role of PSAT1 in determining external serine dependence in cancer." (PMID 40462988, 2025).
cancer (continued). "Collectively, preclinical studies across multiple cancers demonstrate the therapeutic potential of targeting PSAT1 as an antitumor strategy." (PMID 41415540, 2025). "Together with our validation of serine auxotrophy in PSAT1-suppressed primary AML samples, these findings nominate AML as a cancer with substantial potential for therapeutic susceptibility to dietary serine restriction." (PMID 40462988, 2025). "This was evident in other tumors in the TCGA database, where cancer patients with high PSAT1 expression have a shorter overall survival." (PMID 39186541, 2024). "Together, these findings provide key evidence linking serine regulation by PSAT1 metabolism to antitumor immunity in cancer." (PMID 39186541, 2024). "PSAT1 overexpression worsens the prognosis of cancer by encouraging cancer cell proliferation, metastasis, and chemoresistance." (PMID 38785748, 2024). "Previous studies have confirmed that PSAT1 is an oncogene that is usually over-expressed in malignant tumors, especially in non-small cell lung cancer (NSCLC)." (PMID 39872525, 2024). "The PSAT1 plays a key element in the occurrence and development of a variety of tumors, and therefore it is a key point in the study of cancer development 12-16." (PMID 38706897, 2024). "PSAT1, an enzyme involved in serine synthesis, has garnered substantial attention in recent years due to its pivotal role in cancer progression, particularly in relation to invasion and metastasis, a critical aspect in clinical oncology 46,47." (PMID 38706897, 2024). "Phosphoserine aminotransferase 1 (PSAT1) has been reported to affect the progression of various cancers by participating in lipid metabolism processes." (PMID 36900015, 2023). "Among the 33 cancer types we evaluated, PSAT1 was significantly highly expressed in 18 cancers, especially UCEC." (PMID 36906716, 2023). "CDKN2A displayed higher mutation rates across multiple cancer types (31%), and other frequently mutated genes included LRPPRC (13%), PRKAA2 (11%), VLDLR (9%), ASNS (8%), GZMA (7%), GLS (7%), TNFRSF1A (6%), PSAT1 (5%), and PRDX6 (4%)." (PMID 37534256, 2023). "The Cancer Genome Atlas (TCGA) was used to determine the mRNA expression levels of PSAT1 in different cancers." (PMID 36906716, 2023). "Considering that PDLSCs are quite different from these cancer cells, more exploration is required to explain the regulatory network involved in PSAT1 in PDLSCs." (PMID 36732787, 2023). "Given that PSAT1 is involved in the biosynthesis of serine in cells, several studies have supported that PSAT1 regulates the behaviour of cancer cells by regulating serine production." (PMID 36732787, 2023). "Accumulating evidence shows that lncRNAs are interlinked with PSAT1 and play a major role in cancer cell proliferation, angiogenesis and invasion." (PMID 37147729, 2023). "Researchers need to investigate how PSAT1 expression is correlated with pan-cancer tumor microenvironment (TME), as well as examine how PSAT1 expression is correlated with two major immunomodulators." (PMID 36105075, 2022). "We further employed GSEA to investigate the potential biological processes of PSAT1 in pan-cancer according to the results of survival analysis." (PMID 36105075, 2022). "To study the role of PSAT1 in the tumor immune microenvironment, we quantified its expression and immune infiltration levels in Pan-cancers." (PMID 36105075, 2022). "GSEA pathway enrichment analysis results indicated that PSAT1 was markedly abundant in the cell cycle signaling pathway, while cell cycle signaling pathway is closely related to cancer cell proliferation." (PMID 35615948, 2022). "Building on the correlation between PSAT1 and immune checkpoints, we took a step further to assess the therapeutic efficacy of immunotherapy for pan-cancer." (PMID 36105075, 2022). "PSAT1 is generally overexpressed in malignant tumors, and plays an important role in regulating tumor progression." (PMID 36699468, 2022).
cancer (continued). "The results of RT-PCR in tissues demonstrated that IYD, ACADSB, and PSAT1 had significantly lower expression levels in cancer tissues than in adjacent tissues, consistent with the predicted results." (PMID 36118874, 2022). "It is reported that PSAT1 level is enforced in tumor tissue and is related to cancer cell proliferation." (PMID 35615948, 2022). "For this reason, the “Pathological Stage Plot” module of GEPIA2 was employed to investigate the correlation of PSAT1 expression and cancer pathological stages." (PMID 36105075, 2022). "In the rescue experiments, levels of these proteins in cancer cells were restored due to the restoration of PSAT1." (PMID 35615948, 2022). "Based on TCGA database, we examined the status of genetic alteration of PSAT1 in various kinds of cancers." (PMID 36105075, 2022). "The results found that PSAT1 can be enriched into the classic signaling pathways of cancer such as mTORC1 signaling, MYC targets and JAK STAT3 signaling." (PMID 36105075, 2022). "It was confirmed that PSAT1 expression is enforced in tumor tissue and is related to cancer cell proliferation." (PMID 35615948, 2022). "The Gene Set Enrichment Analysis (GSEA) analysis showed that PSAT1 can be enriched into the classic signaling pathways of cancer such as mTORC1 signaling, MYC targets and JAK STAT3." (PMID 36105075, 2022). "The key SSP enzymes PHGDH, PSAT1, and PSPH are significantly overexpressed in a variety of cancers and are associated with poor patient outcomes." (PMID 36699468, 2022). "The function of PSAT1 in diseases, including cancer, is being studied in ever-increasing numbers of studies." (PMID 36105075, 2022). "Nevertheless, high PSAT1 expression levels were associated with an improved OS prognosis in LGG and GBM (p = 6.7e-09) cancers." (PMID 36105075, 2022). "Here, we performed an integrated pan-cancer analysis to explore the potential molecular mechanisms of PSAT1 in cancers." (PMID 36105075, 2022). "CCK-8 assay result illustrated that overexpressed microRNA-145-5p markedly inhibited the proliferative viability of cancer cells, while the viability was notably restored in the microRNA-145-5p mimic+oe-PSAT1 group." (PMID 35615948, 2022). "In this study, we used the data available in the public database to conduct a comprehensive pan cancer analysis of PSAT1 to determine the correlation between its expression and the prognosis of various malignant tumors." (PMID 36105075, 2022). "Among the 24 potential genes, HSP90AA1, ANXA1, ARRDC4 and PSAT1 were involved with cancer progression." (PMID 34916487, 2021). "The over-expression of PSAT1 is a marker of poor prognosis in cancer patients and even increases the resistance of chemotherapy." (PMID 33763366, 2021). "PSAT1 is up-regulated in many cancers and acts as an oncogene that exerts a vital role in cancer progression and metastasis." (PMID 32737333, 2020). "The phosphoserine aminotransferase 1 (PSAT1) and branched-chain amino acid transaminase 1 (BCAT1) were upregulated in many carcinoma tissues and associated with cell proliferation." (PMID 32509585, 2020). "From a literature review, overexpression of PHGDH, PSPH and PSAT1 proteins are known to lead to poor outcomes in various cancers." (PMID 31861486, 2019). "APC and SCGB3A1 disclosed 100% specificity for cancer detection, whereas PSAT1 showed the highest sensitivity (91.97%)." (PMID 30405052, 2018). "A growing amount of evidence has indicated that PSAT1 is an oncogene that plays an important role in cancer progression and metastasis." (PMID 29216929, 2017). "There are also evidences of de-regulated expression in cancer of two other enzymes of serine biosynthesis – PSAT1 and PSPH." (PMID 28177894, 2017). "Consistent with its oncogene function, TAZ S89A induced expression of the ERMS cancer stem cell gene Myf5 and the serine biosynthesis pathway (Phgdh, Psat1, Psph) in C2C12 myoblasts." (PMID 27184927, 2016).
cancer (continued). "TAZ S89A drove increased expression of the cancer‐related genes Phgdh, Psat1, Psph and Myf5, although Ctgf mRNA levels were unchanged." (PMID 27184927, 2016). "Mullen and DeBerardinis seemingly agree, stating that cancer cells (at least in culture) express a number of other highly active transaminases in addition to PSAT1 which often account for the majority of glutamine-derived aKG." (PMID 25574168, 2014). "It will be interesting to see as future studies unfold why a subset of cancer cells appear to preferentially use PSAT1 as a source for aKG." (PMID 25574168, 2014). "Notably, PSAT1-mediated cancer-derived EVs promote osteoclast differentiation and accelerate bone metastasis, highlighting this pathway as a potential therapeutic target for inhibiting metastatic progression, supported by in vitro and in vivo models." (PMID 41465584, 2025). "PHGDH and PSAT1 are up-regulated in ERneg BC, and both have important roles in cancer development." (PMID 40117373, 2025). "Our data revealed an increase in serine and related metabolites, along with an increased expression of serine/folate transporters in undifferentiated cancer, but there was no increase in expression of SSP-related genes, such as PHGDH, PSPH, and PSAT1, compared to differentiated cancer." (PMID 38331894, 2024). "The relationship between PERK and PSAT1-mediated serine biosynthesis opens up possibilities for reprogramming or editing M2 macrophages, which may benefit the treatment of cancer or other inflammatory diseases." (PMID 37938371, 2024). "GLDC was found to be involved in cancer growth through the PSAT1/Serine/SHMT/GLDC/Glycine complex." (PMID 39149564, 2024). "One key player manipulating cancer cells’ metabolic pathways is PSAT1." (PMID 39186541, 2024). "PSAT1 knockout significantly reduced the lung metastasis of cancer cells in vivo." (PMID 36788227, 2023). "Our findings are similar to previous studies that reported that ATF4 could influence PSAT1 expression in some cancer cells." (PMID 36732787, 2023). "However, beyond the limited information provided by these studies, the role of PSAT1 in malignant tumors is still unclear." (PMID 36105075, 2022). "Phosphoserine aminotransferase 1 (PSAT1) may be an oncogene that plays an important role in various cancer types." (PMID 36105075, 2022). "According to these findings, PSAT1 is a potential biomarker for cancer prognosis prediction." (PMID 36105075, 2022). "By pan-cancer analysis, PSAT1 could affect the tumor immune microenvironment by immune infiltration analysis." (PMID 36061202, 2022). "Additionally, we examined differences in the expression of PSAT1 within the same cancer at different stages after analyzing PSAT1 expression in different cancer types." (PMID 36105075, 2022). "Based on PFS analysis data, high PSAT1 expression was associated with poor PFS in LUAD (p = 1.5e-06), KIPAN (p = 1.3e-08), KIRC (p = 4.5e-08), MESO (p = 3.8e-05), KICH (p = 6.8e-04), KIRP (p = 2.2e-03) and BRCA (p = 2.1e-02) cancers." (PMID 36105075, 2022). "To determine whether high PSAT1 methylation may induce sensitivity to S/G deprivation in additional tumor types, we analyzed PSAT1 methylation and gene expression in the TCGA Pan-Cancer Atlas dataset." (PMID 35045283, 2022). "In addition, PSAT1 was found to promote extracellular vesicle (EV) secretion via the serine-ceramide synthesis pathway in multiple cancer types, affecting the tumor microenvironment." (PMID 36061202, 2022). "This study combined gene expression, gene mutation, methylation, immune microenvironment, pathway enrichment, and survival prognosis to comprehensively detect the expression of PSAT1 gene in different cancers on account of data from the TCGA, GEO, and CPTAC databases." (PMID 36105075, 2022).